GIPR (gastric inhibitory polypeptide receptor)
Diseases named in the same sentence as GIPR in open-access papers (continued):
Sharing a sentence is not in itself a finding about the gene and the disease.
breast carcinoma (1 paper, 2023). "Our findings, using an established missense variant in GIPR to proxy impaired GIPR signaling, suggest potential adverse effects of downregulated GIPR signaling on breast cancer risk and, thus, possible protective effects of pharmacological GIPR agonism." (PMID 37250804, 2023). "In conclusion, our drug-target MR analyses across 6 cancers suggest adverse effects of the GIPR E354Q missense variant on breast cancer risk." (PMID 37250804, 2023). "Our human genetics analysis suggests an adverse effect of the GIPR E354Q variant on breast cancer risk, supporting further evaluation of GIPR signaling in breast cancer prevention." (PMID 37250804, 2023). "Adipokines, including adiponectin and resistin, have previously been linked to breast cancer risk in conventional observational studies and could provide another potential mechanism linking GIPR signaling to breast cancer risk." (PMID 37250804, 2023). "These measures confer opposing effects on breast cancer risk, suggesting perturbed glycemic and/or other adverse effects of impaired GIPR signaling through this mechanism offset possible beneficial effects on insulin secretion and circulating testosterone levels." (PMID 37250804, 2023). "Alternatively, the specificity of the association of E354Q with breast cancer risk could reflect a potentially unique role of GIPR signaling in breast carcinogenesis." (PMID 37250804, 2023). "Given the sparsity of preclinical and epidemiological literature examining the role of GIPR signaling in breast cancer development, further work is warranted to validate and clarify potential mechanisms underpinning this putative effect." (PMID 37250804, 2023). "Triangulation of these findings in other settings will inform on the efficacy of pharmacologically modifying GIPR signaling as a potential chemoprevention strategy for breast cancer." (PMID 37250804, 2023). "Evaluation of the role of genetically proxied GLP1R signaling, alone and in combination with genetically proxied GIPR signaling, could provide additional insight into the viability of dual pharmacological GLP1R/GIPR agonism for breast cancer prevention." (PMID 37250804, 2023). "Our findings suggest that a potential adverse effect of impaired GIPR signaling on breast cancer risk is unlikely to be mediated via insulinemic and/or hormonal pathways." (PMID 37250804, 2023). "In particular, further evaluation of possible non-insulinemic pathways influenced by GIPR signaling could help to reconcile the specificity of the E354 association with breast cancer risk given the important role of metabolic dysfunction across the 5 other cancers examined in this analysis." (PMID 37250804, 2023). "In this MR analysis of up to 235,698 cancer cases and 333,932 controls, each copy of the GIPR E354Q missense variant was associated with a higher risk of overall, luminal A-like, and luminal B HER2 negative-like breast cancer risk." (PMID 37250804, 2023).
bronchial neuroendocrine tumors (1 paper, 2021). "GIPR is found in many cancers, including the majority of pancreatic, ileal, and bronchial neuroendocrine tumors (NETs)." (PMID 34868990, 2021).
cardiomyopathy (1 paper, 2025). A disease of the heart muscle or myocardium proper. "In summary, GIPR signal inhibition shows cardioprotective effects under conditions of ischemic injury and MI, while GIPR signal amplification shows cardioprotective effects in animal models for cardiomyopathy." (PMID 40024571, 2025).
emesis (1 paper, 2022). "The effects of blocking the GIPR in GIP- and T-2 toxin-induced emesis were evaluated." (PMID 35737050, 2022).
fibrosis (1 paper, 2024). the formation of excess fibrous connective tissue in an organ or tissue in a reparative or reactive process. "First, we checked the expression of both GLP1R and GIPR in a public dataset (GEO accessions GSE135251) consisting of bulk RNA sequencing results from samples of patients with MASH at various fibrosis stages and healthy liver controls." (PMID 39607493, 2024).
fracture (1 paper, 2021). "None of the two GIPR variants seemed to be associated with an overall risk of bone fracture." (PMID 34760890, 2021).
homeostasis (1 paper, 2023). "Jeannine group investigated the association of variants in GIPR gene with impaired glucose homeostasis in obese children and adolescents from Berlin." (PMID 36882778, 2023).
ischemic stroke (1 paper, 2024). A stroke disorder caused by obstruction of blood flow to the brain, due to thrombotic (local blood clot formation) or embolic (due to a blood clot or other material traveling from another site) event. "Despite an association of genetically proxied GIP/GIPR agonism with a favorable cardiometabolic risk profile (including higher BMI and HDL cholesterol), there was no strong evidence of association with ischemic stroke risk." (PMID 39628323, 2024).
liver disease (1 paper, 2025). "Given the well-established role of alcohol in liver disease progression, larger and more refined ALD GWAS datasets are necessary to clarify whether GIPR and GLP1R agonism directly mitigates ALD risk." (PMID 40931165, 2025). "We next investigated the impact of GIPR and GLP1R modulation on liver disease and liver enzyme outcomes using GWAS summary statistics from European-ancestry cohorts." (PMID 40931165, 2025).
lung adenocarcinoma (1 paper, 2024). A carcinoma that arises from the lung and is characterized by the presence of malignant glandular epithelial cells. "Interestingly, neither epithelial and stromal gastrointestinal (GI) tumors and GI stromal tumors nor lung adenocarcinomas express GIPR, except for a subgroup of pancreatic adenocarcinomas." (PMID 38730608, 2024).
metastasis (1 paper, 2024). The spread or migration of cancer cells from one part of the body (where they first appeared) to another. "Furthermore, increased GIPR expression has been correlated with liver metastasis." (PMID 38730608, 2024).
migraine (1 paper, 2022). "Receptors directly associated with migraine or pain include endothelin receptor type B (EDNRB), GIPR, and hypocretin receptor 1 (HCRTR1)." (PMID 35453627, 2022).
nephrolithiasis (1 paper, 2024). The presence of a calculus in the pelvis of the kidney; this is most often composed of mineral salts and proteins. "The effect of weight loss through glucagon-like peptide 1 (GLP-1) receptor agonists and dual GLP-1/gastric inhibitory polypeptide receptor agonists (GLP-based therapies) on nephrolithiasis is not well understood." (PMID 39298632, 2024).
neuroblastoma (1 paper, 2020). Neuroblastoma (NB) is the most common solid, extracranial childhood tumor. "To understand GIPR desensitization in other cell types, we utilized mouse Neuro-2a neuroblastoma and rat INS1 832/13 islet cell lines." (PMID 33020469, 2020).
non-alcoholic fatty liver disease (1 paper, 2024). "GIPR produces effects in non-alcoholic fatty liver disease and liver fat." (PMID 39764438, 2024).
pancreatic cancer (1 paper, 2023). "The experimental results showed that the mRNA expression levels of EMP1, GIPR, SFRP1, CXCL11 and COL17A were significantly high in the pancreatic cancer cell line compared with the controls." (PMID 37547756, 2023).
pancreatic NETs (1 paper, 2022). "GIPR was significantly higher in neuroendocrine tumors (NETs), such as functional pancreatic NETs (including insulinomas), gastrinomas, and non-functional pancreatic NETs, compared to non-neoplastic tissue." (PMID 36358930, 2022).
pituitary tumor (1 paper, 2020). A benign or malignant neoplasm affecting the pituitary gland. "GIPR expression varies in adrenal and pituitary tumors, and neuroendocrine tumors, but - regardless of the tumor’s type and origin, cAMP signaling is activated in all GIPR-positive tumors and not in GIPR-negative ones." (PMID 32498358, 2020).
renal carcinoma (1 paper, 2023). A carcinoma arising from the epithelium of the renal parenchyma or the renal pelvis. "In colocalization analysis, there was little evidence to support one or more shared causal variants for fasting or 2-h GIP concentrations and renal cancer risk in GIPR (H4<21.2%)." (PMID 37250804, 2023).
retinoblastoma (1 paper, 2024). A malignant tumor that originates in the nuclear layer of the retina. "Next, we investigated GIPR’s expression levels in retinoblastoma primary tumor tissue and correlated them with TFF1 expression." (PMID 38730608, 2024). "To further study the functional role of GIPR in RB, we overexpressed GIPR in Weri and Y79 retinoblastoma cells." (PMID 38730608, 2024). "Our results indicate a tumor suppressor role of GIPR in RB, suggesting its pathway as a new potential target for future retinoblastoma therapy." (PMID 38730608, 2024).
steatosis (1 paper, 2023). Increased lipid within the cytoplasm of cells. "Furthermore, microvascular steatosis was lower upon GLP1R agonism, but not GIPR agonism, while combined GIPR/GLP1R agonism led to a pronounced reduction in microvascular steatosis even when compared to single GIPR and GLP1R agonism." (PMID 37379656, 2023).
tumor (13 papers, 2018 to 2025). "An ectopic GIP/GIPR axis in tumor somatotroph cells causes ~ 80% of cases of the paradoxical responses of GH." (PMID 37344722, 2024). "Exemplary immunohistochemical stains of RB patient tumor sections revealed that TFF1+ tumors are also positive for GIPR, whereas TFF1-tumors also stain negatively for GIPR." (PMID 38730608, 2024). "The quantification of CAM tumor weight and size revealed that both GIPR-overexpressing RB cell lines investigated formed significantly lighter and smaller tumors in ovo than the control cells." (PMID 38730608, 2024). "Next, we used the chicken chorioallantoic membrane (CAM) assay to examine the impact of GIPR overexpression on RB cell tumor growth and formation capacity in an in vivo model (for the schematic depiction)." (PMID 38730608, 2024). "TFF1-expressing (TFF1-positive; TFF1+) RB tumor cells, by contrast, showed significantly increased GIPR expression compared to TFF1-RB tumor cells and compared to hRet." (PMID 38730608, 2024). "Fittingly, in the study hereby presented, the increase in apoptosis seen after GIPR overexpression in RB tumor cells was likewise caspase-3-dependent." (PMID 38730608, 2024). "In adrenal lesions of these patients, the loss of histone demethylase KDM1A, which acts in this context as a tumor suppressor gene, reduces the condensation of chromatin with subsequent overexpression of GIPR." (PMID 37298217, 2023). "The in vivo tissue background and excretion patterns were favorable for potential tumor and liver metastases localization, but binding to the GIPR-dense tissues was low." (PMID 36678558, 2022). "Co-administration of an excess unlabeled GIP1-42 significantly lowered tumor uptake to 0.8 ± 0.2%ID/g (p = 0.0001) 4 hours after injection, indicating GIPR-mediated tumor uptake." (PMID 29440684, 2018). "Although [Lys37(111In-DTPA)]N-acetyl-GIP1-42 showed high and specific tumor uptake in GIPR-transfected GIPR tumors, tumor uptake in NES2Y tumors was lower and co-injection of an excess unlabeled GIP1-42 did not result in significantly lower tracer uptake." (PMID 29440684, 2018). "Optimal GIPR-mediated tumor targeting of BHK-GIPR positive tumors in vivo, was observed 1 hour post injection using a peptide dose of 0.2 μg (0.04 nmol)." (PMID 29440684, 2018). "The presented analysis of both bulk- and scRNAseq data confirms that these double-positive sPitNETs are the ones that express high levels of GIPR and expression of this gene distinguishes the tumor cells of this subtype from normal pituitary somatotrophs, which are GIPR-negative." (PMID 40813692, 2025). "Next, we set out to investigate how GIPR expression is regulated in RB tumor cells." (PMID 38730608, 2024). "Moreover, GIPR-overexpressing RB cells developed significantly smaller tumors in vivo, indicating a tumor suppressor role of GIPR in RB." (PMID 38730608, 2024). "However, the tumor uptake in absolute terms was very low (SUV < 1), which is hardly suitable for sensitive in vivo detection of GIPR-expressing neoplasms." (PMID 36678558, 2022). "Thus, in summary, the in vitro data demonstrated strong GIPR-mediated binding to cell lines and relevant tumor biopsies supporting further in vivo evaluation." (PMID 36678558, 2022). "Therefore, we optimized the radiolabeling procedure and investigated its binding and internalization kinetics using GIPR-positive tumor cells (BHK-GIPR)." (PMID 29440684, 2018). "Moreover, while TFF1-negative RB tumor cells displayed similar GIPR levels to healthy human retina, significantly increased GIPR expression levels were detected in TFF1-positive primary tumor cells, representing the subset of more advanced RBs with TFF1 as an indicating biomarker." (PMID 38730608, 2024).
tumor (continued). "The analogs demonstrated specific internalization into GIPR-transfected pancreatic endocrine cells (INR1G9-huGIPR) and specific tumor uptake in INR1G9-huGIPr mouse xenografts." (PMID 36678558, 2022). "Compared to the controls, the tumor formation capacity was not significantly changed in the GIPR-overexpressing Weri and Y79 cells." (PMID 38730608, 2024). "Our analysis identified seven tumour suppressor genes (ITGA7, SLC45A1, TPPP, SCN4A, GIPR, SOGA3 and RAB6B) and six oncogenes (SAT1, SERPINE1, UPK2, SYT12, RASAL1 and CDH3) with significant false discovery rate (FDR)-adjusted P values (q-value) of less than 0.05." (PMID 38429478, 2024). "Real-Time PCR analyses revealed that cultured primary RB patient-derived tumor cells, which do not express TFF1 (TFF1-negative; TFF1) displayed similar GIPR levels to healthy human retina (hRet)." (PMID 38730608, 2024).
cancer (8 papers, 2021 to 2025). A tumor composed of atypical neoplastic, often pleomorphic cells that invade other tissues. "The relationship between GIPR signaling and the risk of cancers influenced by impaired glucose homeostasis is unclear." (PMID 37250804, 2023). "The high GIPR content in a broad spectrum of cancers, makes GIPR a potential target for cancer diagnostic and therapeutic purposes." (PMID 34868990, 2021). "Most of the GO terms were related to “apoptosis”, “proliferation”, “cell migration”, “cell cycle”, and “angiogenesis”, all processes playing an important role in cancer and shown to be affected by GIPR overexpression in RB cells." (PMID 38730608, 2024). "Recent studies involving paired administration of both incretins—GIP and GLP1— observed that GIP suppressed some adverse behavioral responses to GLP1; furthermore, GIPR agonists reduced morphine- and cancer-drug-induced vomiting in ferrets." (PMID 35705049, 2022). "We speculate that drugs that target both GLP-1R and GIPR might have better effectiveness against cancers with high expression of both receptors, such as pancreatic, thyroid, breast, and lung cancers." (PMID 41178720, 2025). "This discrepancy might be explained in terms of comparing the effects of metabolic signaling along the GIP/GIPR axis with the pathological conditions of a cancer cell line." (PMID 38730608, 2024). "Whether TRZD could have similar anti-cancer effects through the activation of the GLP-1R/GIPR is yet to be determined." (PMID 36358930, 2022). "Comparatively, GIPR, which is targeted by dual agonists (e.g., tirzepatide), is expressed in many cancers, while the glucagon receptor (GCGR), which is targeted by triple agonists (e.g., retatrutide), is only detected in a few cancer types." (PMID 41178720, 2025).
metabolic disease (8 papers, 2019 to 2026). A congenital disorder (due to inherited enzyme abnormality) or acquired (due to failure of a metabolically important organ) disorder resulting from an abnormal metabolic process. "Our data highlights the distinct metabolic effects of GIPR agonism and antagonism, offering insights for their future application in personalised metabolic disease treatments." (PMID 41287212, 2026). "To date, the majority of such agents being developed to treat metabolic diseases possess activity at the GLP-1R as the anchor pharmacophore but are also agonists for either the GIPR, the glucagon receptor, or both." (PMID 32730231, 2020). "In recent years, there has been a resurgence of interest in targeting the glucose‐dependent insulinotropic polypeptide receptor (GIPR), alongside the glucagon‐like peptide 1 receptor (GLP‐1R), for the treatment of metabolic disease." (PMID 41287212, 2026). "This evidence underscores the promise of GIPR agonism as a therapeutic avenue for addressing AUD and comorbid metabolic disorders, warranting further investigation in clinical settings." (PMID 40931165, 2025). "In the present work we extend these observations to GIPR and GCGR, members of the same class B GPCR family and major investigational targets for metabolic disease." (PMID 33268378, 2021).
cardiovascular disease (5 papers, 2010 to 2024). "An earlier study in European population looked at the role of common variants in GIPR and GIP with cardiovascular diseases." (PMID 20673334, 2010).
neurodegenerative disease (1 paper, 2025). A disorder of the central nervous system characterized by gradual and progressive loss of neural tissue and neurologic function. "Early-stage clinical studies of dual GLP-1 and gastric inhibitory polypeptide receptor agonists in neurodegenerative disease further support the relevance of GIPR gene." (PMID 41301891, 2025).
respiratory system diseases (1 paper, 2025). "Previous studies showed an association between GIPR and C-reactive protein levels and ITPKA was found to be related to respiratory system diseases, while PIK3C2B was reported to be associated with lung function." (PMID 40251596, 2025).
GIPR also shares sentences with these, for which no sentence is quoted: Stroke (3 papers); Anorexia (2); coronary artery disease (2); hypercortisolemia (2); somatotroph adenomas (2); adrenal hyperplasia (1); anxiety disorder (1); central obesity (1); cognitive deficit (1); connective tissue disorder (1); diabetic ketoacidosis (1); diabetic nephropathy (1); diabetic retinopathy (1); food-dependent Cushing’s syndrome (1); genetic disease (1); glaucoma (1); growth deficiency (1); hypoparathyroid (1); malaise (1); memory impairment (1); neurological disorders (1); obstructive sleep apnea (1); osteosarcoma (1); pancreatic adenocarcinoma (1); scoliosis (1); social phobia (1); thyroid cancer (1); triple-negative breast carcinoma (1).